NGF (nerve growth factor)
Diseases named in the same sentence as NGF in open-access papers (continued):
Sharing a sentence is not in itself a finding about the gene and the disease.
pancreatic cancer (continued). "Moreover, hyperglycemia supports the multiplication and invasion of pancreatic cancer cell lines and induces the expression of NGF in these cells, increasing the interaction between the nerves and cancer cells." (PMID 39723256, 2024). "Pancreatic cancer cells secrete nerve growth factor (NGF), impacting Schwann cells." (PMID 38567163, 2024). "Pancreatic cancer cells can induce SC autophagy through NGF/ATG7 paracrine pathway." (PMID 39906323, 2024). "Indeed, the inflammatory environment of pancreatic cancer and chronic pancreatitis stimulates the production of neurotrophic mediators, such as nerve growth factor (NGF), artemin, and neurturin." (PMID 38541624, 2024). "Another study investigated whether gold nanocluster-assisted NGF-siRNA delivery (GNC-siRNA) provides effective NGF gene silencing and pancreatic cancer therapy." (PMID 37981671, 2023). "Furthermore, the expression of NGF was detected by western blotting revealed that activating the HGF/c-Met signaling pathway promotes NGF expression in the pancreatic cancer cell lines PANC-1 cells and BxPC-3 cells." (PMID 35449152, 2022). "In addition, NGF also can promote the invasion and migration of liver cancer cells, prostate cancer cells, and pancreatic cancer cells." (PMID 35449152, 2022). "The combination of an NGF inhibitor and chloroquine can prevent the occurrence and development of perineural invasion in pancreatic cancer, and potential molecular neurotrophic factors, such as NGF, secreted by cancer cells can induce autophagy of SCs by upregulating ATG7 expression." (PMID 35109895, 2022). "NGF/tropomyosin-related kinase A (TrkA) promotes PanCa cell proliferation and invasion in a pancreatic stellate cell-pancreatic cancer cell coculture system via activation of PI3K/AKT/GSK signaling, which may be a potential therapeutic target for PC patients." (PMID 35109895, 2022). "Although the exact mechanism is not clear, it is highly likely that p75NTR may predispose tumor cells to perineural invasion, conferring responsivity to NGF-producing Schwann cells and neurons, as reported in oral cancer and pancreatic cancer." (PMID 35681602, 2022). "The activation of the mTOR signaling pathway and the autocrine of NGF may together promote the invasion and migration ability of pancreatic cancer cells." (PMID 35449152, 2022). "Lei et.al revealed that NGF contributed to the proliferation and metastasis of pancreatic tumors." (PMID 36522730, 2022). "Growth factors such as nerve growth factor and neurotransmitters such as dopamine and norepinephrine which are secreted by neurons have been shown to act as chemoattractants to breast, gastric and pancreatic cancer cells." (PMID 36333352, 2022). "Similarly, another study showed that NGF knockdown prevented pancreatic cancer cell proliferation, invasion, and migration." (PMID 34195085, 2021). "To further investigate the mast cell degranulation products in tissues surrounding the pancreatic tumors, we examined whether the expression of histamine, tryptase, and NGF was altered in the specimens." (PMID 31201657, 2019). "Therefore, NGF can directly act on these two receptors on visceral primary afferent nerve endings, thus playing a key role in the pathogenesis of pancreatic cancer pain." (PMID 31201657, 2019). "Of note, NGF is also produced in pancreatic cancer cells and its receptors TrKA and P75NTR are expressed on both pancreatic cancer cells and nerves, indicating that these molecules could play a role in PNI." (PMID 31248001, 2019). "In this study, we speculate that mast cells are locally recruited and activated by pancreatic carcinomas and release mediators such as tryptase, histamine, and NGF." (PMID 31201657, 2019).
pancreatic cancer (continued). "The GNC–siRNA complex potently downregulates the NGF expression in Panc-1 cells and in pancreatic tumours, and effectively inhibits the tumour progression in three pancreatic tumour models (subcutaneous model, orthotopic model and patient-derived xenograft model) without adverse effects." (PMID 28440296, 2017). "The data in subcutaneous model reconfirmed our hypothesis that NGF silencing inhibits the progression of subcutaneous pancreatic tumours." (PMID 28440296, 2017). "The suppression of gene expression of nerve growth factor (NGF) may have great potential in pancreatic cancer treatment." (PMID 28440296, 2017). "The NGF depletion with GNC–siRNA complex inhibited both pancreatic tumour growth and intratumoral neurite growth; in turn, the reduced neurogenesis by GNC–siRNA complex reduced the metastasis of pancreatic cancers via nerves by the process of perineural invasion." (PMID 28440296, 2017). "Furthermore, the role of NGF within the pancreatic cancer microenvironment is multifaceted." (PMID 38567163, 2024). "Studies have shown that the activation of Hh signaling pathway is positively related to peripheral nerve invasion in pancreatic cancer and neuropathic pain, and may be related to the upregulation of some neurotrophic factors, such as NGF and matrix metalloproteinases." (PMID 38041128, 2023). "Similarly, NGF withdrawal resulted in pancreatic cancer β Cell apoptosis." (PMID 35874807, 2022). "Additionally, activating mTOR upregulated NGF expression in pancreatic cancer cell lines." (PMID 35449152, 2022). "Thus, NGF targeting has a potential therapeutic value for the treatment of pancreatic cancer." (PMID 36297407, 2022). "Thus, we can speculate that MOR activation as the result of endogenous or exogenous opioids can trigger the release of soluble factors (i.e., nerve growth factor) that promote neurogenesis within the pancreatic cancer microenvironment." (PMID 34222012, 2021). "In response to auto- or paracrine-released nerve growth factor (NGF), the MAPK/ERK pathway is activated through the TrkA receptor, leading to the activation of ERKs within pancreatic cancer stem cells (PCSCs)." (PMID 39891818, 2025). "In the subcutaneous pancreatic cancer model, compared with the saline control group, the tumor volume of mice treated with GNC-siRNA decreased by 52%, and the NGF mRNA of mice treated with GNC-siRNA decreased by 69%." (PMID 39128942, 2024). "Studies have found that activation of this signaling pathway can elevate the expression levels of NGF and its receptors in DRG cells, which then promotes the expression and secretion of SP and CGRP, exacerbating the pain of pancreatic cancer." (PMID 38567163, 2024). "Activation of the NGF-TRKA pathway, through the PI3K/AKT/GSK signaling cascade, augments the proliferative and invasive capacities of pancreatic cancer cells." (PMID 38567163, 2024). "For instance, neural and cancer-derived nerve growth factor (NGF), binding to its receptor TrkA expressed on cancer cells, leads to p44/42 MAPK-mediated MMP-2 overexpression in pancreatic cancer." (PMID 39906323, 2024). "A subcutaneous pancreatic cancer xenograft model was established in nude mice to detect the viability, EMT, and NGF expression of BxPC-3 cells (sh NC vs. sh c-Met)." (PMID 35449152, 2022). "The results illustrate that Nodal upregulates NGF (nerve growth factor), BDNF (brain-derived neurotrophic factor), and GDNF (glial cell line-derived neurotrophic factor) expression in pancreatic cancer cells and promotes cancer cell migration/invasion." (PMID 35126957, 2022). "Our study finds that after rhNodal treatment, neurotrophins (NGF, BDNF, and GDNF) significantly increased in pancreatic cancer cells, and vice versa." (PMID 35126957, 2022). "Then, the pancreatic cancer cell lines PANC-1 and BxPC-3 were used to test the effect of the combination of the NGF inhibitor and chloroquine on cancer cells." (PMID 35109895, 2022).
pancreatic cancer (continued). "In another study, Jiang and coworkers demonstrated the delivery of siRNA complementary to nerve growth factor (NGF) by gold nanoclusters (GNC-siRNA), which lead to the efficient NGF gene inhibition and pancreatic cancer treatment." (PMID 35200353, 2022). "Okada et.al showed that NGF promoted MMP-2 expression and accelerated the invasion of human pancreatic cancer by activating the MAPK pathway." (PMID 36522730, 2022). "Western blot analysis was used to evaluate NGF, BDNF, GDNF, and MMP-9 protein expression in pancreatic cancer cells." (PMID 35126957, 2022). "After pancreatic cancer lines were treated with different concentrations of HNK, Western blotting was applied to detect the expression of NGF and BDNF." (PMID 34671554, 2021). "More importantly, activating SMAD2/3 can upregulate the expression of NGF and BDNF in pancreatic cancer cells and promote the PNI of pancreatic cancer in vitro." (PMID 34671554, 2021). "As the nervous microenvironment has been recognized as a novel niche for PDAC progression and metastasis, nerve growth factor (NGF) and brain derived growth factor (BDGF) are rising targets for pancreatic cancer." (PMID 34683931, 2021). "Overexpression of NGF and BDNF induces noradrenaline accumulation consequently inducing pancreatic cancer cell growth." (PMID 34195085, 2021). "A positive correlation was observed among the expression levels of NGF, p75NTR, TRKA, TRKB, glial cell line-derived neurotrophic factor (GDNF), and PNI in pancreatic cancer tissues or cell lines." (PMID 33392191, 2020). "Herein, we focus on that the Nerve growth factor (NGF)/Tropomyosin‐related kinase A (TrkA), in pancreatic stellate cells‐pancreatic cancer cells (PSCs‐PC cells) co‐culture system, influences PC proliferation and invasion." (PMID 32294802, 2020). "STAT3 leads to the expression of NGF, MMP2, and MMP9 in pancreatic cancer cells so that they can migrate and invade." (PMID 32555170, 2020). "Another intriguing point is the fact that ADRB2 signaling upregulates nerve growth factor (NGF) and brain-derived neurotrophic factor (BDNF) expression in pancreatic cancer, and increased survival was observed in patients treated with nonselective B-blockers." (PMID 32516941, 2020). "The combination of NGF secreted by mast cells with TrkA and/or p75 NTR on nerve fibers directly activates and sensitizes sensory nerves near pancreatic tumors." (PMID 31201657, 2019). "The gold nanocluster (GNC)-assisted delivery of small interfering RNA (siRNA) of nerve growth factor(NGF) (GNC–siRNA) allows efficient NGF gene silencing and pancreatic cancer treatment." (PMID 30424010, 2018). "As a result, the NGF depletion in Panc-1 cells with GNC–siRNA complex significantly reduced the growth, proliferation and migration of pancreatic cancer cells, as well as reduced the neurite sprouting in vitro." (PMID 28440296, 2017). "Here we show that gold nanocluster-assisted delivery of siRNA of NGF (GNC–siRNA) allows efficient NGF gene silencing and pancreatic cancer treatment." (PMID 28440296, 2017). "Paracrine signaling between NGF secreted by the pancreatic cancer cells and TRKA on the surrounding nerves results in increased invasive propensity of the pancreatic cancer cells for these nerves, thereby contributing to PNI." (PMID 27792755, 2016). "We show that knocking down NGF or its receptors, TRKA and p75NTR, or treatment with GW441756, a TRKA kinase inhibitor, reduces the proliferation and migration of pancreatic cancer cells in vitro." (PMID 27792755, 2016). "In pancreatic cancer cells in the presence of TRKA, p75NTR enhances binding of NGF to TRKA and results in increased signaling via the NGF-TRKA pathway." (PMID 27792755, 2016). "Furthermore, nerve growth factor (NGF) stimulates sensory fibers located in the dorsal root ganglia, which plays a crucial role in the pain experienced by individuals with pancreatic cancer." (PMID 41601691, 2026).
pancreatic cancer (continued). "Furthermore, in one study, nerve growth factor (NGF) knockdown effectively suppressed Panc-1 cells and tumor progression in three pancreatic tumor models, including a subcutaneous model, an orthotopic model, and a patient-derived xenograft model." (PMID 37566075, 2023). "Targeting NGF and autophagy for PNI treatment can block nerve infiltration and is expected to provide new directions and an experimental basis for the research and treatment of nerve infiltration in pancreatic cancer." (PMID 35109895, 2022). "NE has also been shown to accelerate pancreatic cancer PNI and progression through the β-AR/PKA/STAT3 signaling pathway in vivo, where the activation of STAT3 upregulates the downstream expression levels of NGF and MMPs." (PMID 33392191, 2020). "In addition, nerve growth factor (NGF) upregulated MMP-2 expression and increased invasiveness in pancreatic cancer cells in vitro." (PMID 32092997, 2020). "Besides, NGF interacts with TRKA and/or p75NTR expressed on the perineurium, thereby, directly activating and sensitizing sensory nerves that are close to pancreatic cancer." (PMID 33392191, 2020). "NGF can thus be considered as an autocrine promoter of PDAC as a result of its production by cancer cells and, a chemotaxin for nerves facilitating neural growth, contact, and high affinity with pancreatic cancer cells thus increasing PNI67." (PMID 30741921, 2019). "The GNC–siRNA complex enhances the specific NGF gene knockdown in Panc-1 cells in vitro and in pancreatic tumours in vivo, leading to effective suppression of tumour growth in three pancreatic tumour models without adverse effects and toxicity." (PMID 28440296, 2017). "Thus, elucidating the molecular mechanism of NGF signaling via its receptors, TRKA and p75NTR in pancreatic cancer cells would help decipher the mechanism of PNI in pancreatic cancer." (PMID 27792755, 2016). "Furthermore, pancreatic cancer cells migrate towards dorsal root ganglia (DRG) in a co-culture assay, indicating a paracrine NGF signaling between the DRGs and pancreatic cancer cells." (PMID 27792755, 2016). "Despite the detailed mechanism is unknown it appears that the interaction of NGF and PHD3 is of clinical interest in human specimens, as high levels of NGF close to neuronal tissue within pancreatic cancer may prevent these cells to undergo apoptosis." (PMID 20978507, 2010). "Moreover, another example that injecting cancer cells into sciatic nerve of nude mice to establish a dorsal root ganglion (DRG) co-culture system with cancer cell lines, found that pancreatic cancer cells induce SCs autophagy via NGF/ATG7 pathway, thus promoting pancreatic cancer PNI." (PMID 40248695, 2025). "Additionally, neurotrophins, including nerve growth factor (NGF), brain-derived neurotrophic factor (BDNF), glial cell line-derived neurotrophic factor (GDNF), and chemokines and neurotransmitters exert various effects in regulating PNI in pancreatic cancer." (PMID 35449152, 2022). "Furthermore, many soluble factors of neurotrophic or axon-guiding nature such as NGF, brain-derived neurotrophic factor (BDNF), neurotrophin 3 (NT-3), glial-cell-derived neurotrophic factor (GDNF), neurturin, artemin, sonic hedgehog, SEMA3D, and others are overexpressed by pancreatic tumour cells." (PMID 35269454, 2022). "Finally, blocking NGF signaling by NGF neutralizing antibodies or GW441756 inhibited the neurite formation in PC-12 cells in response to conditioned media from pancreatic cancer cells, indicating a reciprocal signaling pathway between the pancreatic cancer cells and nerves." (PMID 27792755, 2016). "Notably, it has emerged that there is a crosstalk between the neurotrophin pathway, particularly the nerve growth factor (NGF)-NTRK1 axes, and GPCR signaling mediated by either (nor)adrenaline-ADRB2 in pancreatic cancer, or acetylcholine-CHRM1 and CHRM3 in gastric cancer." (PMID 38723607, 2024).
Stroke (74 papers, 2009 to 2025). Sudden impairment of blood flow to a part of the brain due to occlusion or rupture of an artery to the brain. "Nerve growth factor (NGF) is another biomarker associated with functional recovery following stroke." (PMID 40969674, 2025). "BDNF, a nerve growth factor linked to neuronal survival, is associated with increased stroke risk in SCD patients, especially with higher transcranial Doppler (TCD) velocities." (PMID 39749215, 2024). "Furthermore, it was shown that the carriage of the NGF rs6330*T minor allele is associated with increased infarct volume and higher risk of recurrent stroke." (PMID 29499660, 2018). "Our previous study demonstrated that NYT, in combination with exercise, exerts neuroprotective effects by enhancing BDNF and NGF levels after stroke in rats." (PMID 40361157, 2025). "Previous studies have shown that physical exercise increases the upregulation of brain neurotrophic factors such as BNDF and NGF after stroke." (PMID 40361157, 2025). "Stroke and Traumatic Brain Injury: Systemic delivery of neurotrophic factor-loaded EVs (e.g., BDNF, NGF, miR-124) via intravenous or intranasal routes significantly improved neurological recovery and reduced infarct volume in rodent stroke models." (PMID 41155971, 2025). "NGF plays a critical role in the growth, maintenance, and survival of afferent neurons, making it a key factor in post-stroke neural repair." (PMID 40969674, 2025). "In stroke therapy, EVs loaded with nerve growth factor (NGF) (e.g., RVG-EV) notably enhance NGF expression in the infarcted region, reduce inflammation, and promote cell survival." (PMID 40438295, 2025). "Intranasal NGF stimulates neo-angiogenesis post stroke and enhances brain blood flow and metabolism, mechanisms relevant to its therapeutic benefits observed in TBI patients." (PMID 40573325, 2025). "This is consistent with the results of a previous study, which found that TMS treatment reduced glioblastogenesis and promoted the expression of BDNF and NGF in the peri-infarct area after stroke." (PMID 40948655, 2025). "Optogenetic stimulations post-stroke resulted in a beneficial increase in NGF, BDNF, and GAP-43 levels." (PMID 38397420, 2024). "Researchers are also exploring the use of NGF in combination with stem cell therapy to stimulate the growth of new neurons in the brain, particularly after stroke or in neurodegenerative disorders." (PMID 40153582, 2024). "This study will provide clinical evidence for the efficacy and safety of SMES combined with NGF in the treatment of stroke patients." (PMID 39033586, 2024). "Blocking transient receptor potential vanilloid 2 (TRPV2) in astrocytes has been reported to increase astrocyte proliferation, nerve growth factor (NGF) mRNA synthesis, and NGF secretion, which have neuroprotective effects in the early stages of stroke." (PMID 37728588, 2024). "For example, NGF protected bone marrow MSCs against apoptosis, and transplanted NGF‐overexpressing MSCs exhibited increased cell migration in the ischemic brains of stroke rats, primarily mediated by the high‐affinity receptor TrkA." (PMID 38333908, 2024). "In this perspective, growth factors like NGF have been explored to study their neuroprotective and regenerative therapeutic potentials in stroke and TBI." (PMID 40153582, 2024). "It has been demonstrated that NGF can protect sensory neurons and promote neurogenesis in the damaged area after stroke." (PMID 36741282, 2023). "Brain-Derived Neurotrophic Factor (BDNF) is a nerve growth factor associated with elevated transcranial Doppler (TCD) velocities and increased risk of stroke in SCD patients." (PMID 36774398, 2023). "On the other hand, for the survival of newly generated neurons after stroke, the NGF is also involved in angiogenesis after acute stroke in rats." (PMID 36741282, 2023). "Transplantation of nerve growth factor (NGF) and Noggin overexpressed BMSCs significantly facilitated the survival of BMSCs in stroke." (PMID 35695696, 2022).